IGF1R (insulin like growth factor 1 receptor)
Diseases named in the same sentence as IGF1R in open-access papers (continued):
Sharing a sentence is not in itself a finding about the gene and the disease.
tumor (continued). "These limitations underscore the potential advantage of targeting the upstream GH–GHR axis, which can simultaneously reduce circulating IGF1 levels, suppress IGF1R signaling in the TME, and attenuate tumor-promoting pathways." (PMID 41515995, 2025). "Similar to most cancer types, IGF1R is targeted by miR-99a-5p and miR-100-5p in ESCC, resulting in the suppression of tumor cell proliferation, migration, invasion, and SLUG-induced EMT." (PMID 40161350, 2025). "Specifically, the average tumor weight at the experimental endpoint was 1.96 g in the CpG control group, whereas it was reduced to 1.14 g in the TOP2A group, 1.58 g in the IGF-1R group, 1.47 g in the HIF-1α group, and 0.32 g in the TNBCvax group (p<0.001)." (PMID 40969744, 2025). "Compound 7p, in particular, displayed strong affinity for key cancer-related targets such as HSP90, IGF1R, HDAC2, CDK6, HDAC8, and PIK3CA, all of which are involved in tumour proliferation, survival, and metastasis." (PMID 41463373, 2025). "They reported EGCG reduced tumor‐induced HIF‐1α by inhibiting cancer‐induced insulin receptor (IR) and IGF1R." (PMID 40755497, 2025). "The TNBCvax groups also demonstrated a notable decrease in tumor weight relative to the HIF-1α and IGF-1R groups." (PMID 40969744, 2025). "Therapeutically, we demonstrate that the dual IR/IGF1R inhibitor linsitinib restored TKI sensitivity in vitro and synergized with surufatinib to reduce tumor burden and Ki-67 indices in an orthotopic model." (PMID 41275311, 2025). "IGF1R inhibitors, such as BMS-754807 and NVP-AEW541, are being tested and show potential in reducing tumor growth in animal models." (PMID 39918792, 2025). "Separately, it has been observed that CAFs can suppress the insulin‐like growth factor‐1 receptor (IGF‐1R) signaling through their distinct secretome, particularly via abundant IGFBP2, thereby sensitizing resistant tumor cells to conventional antitumor agents." (PMID 41498024, 2025). "MZF1 promotes various types of cancers by targeting key regulators of tumor progression, including c-Myc, AXL, IGF1R, and PKCα." (PMID 40961095, 2025). "Despite extensive exploration of IGF1R inhibitors and IGF1-targeting strategies in cancer therapy, their clinical efficacy has been limited in inhibiting tumor progression." (PMID 41515995, 2025). "It serves as an E3 ligase for histone deacetylase 3 (HDAC3), forkhead box O4 (FOXO4), and insulin-like growth factor 1 receptor (IGF-1R), affecting cellular migration, metabolic adaptation, and tumor growth." (PMID 41170373, 2025). "The results demonstrate that TNBCvax significantly inhibits and delays tumor development compared to the CpG group and other single vaccine-treated groups, including HIF-1α, IGF-1R, and TOP2A." (PMID 40969744, 2025). "Further experiments confirmed that the combined inhibition of IGF-1R (e.g., with linsitinib) or PI3K (e.g., with buparlisib) significantly enhanced the antitumor effects of BLZ945 and prolonged survival in tumor-bearing mice." (PMID 41002423, 2025). "This dysregulation contributes to tumor growth and resistance to apoptosis, positioning IGF2/IGF1R as an important target for therapy in ACC." (PMID 40145087, 2025). "Compounds 910 and 911 showed more potent inhibitory effects against ALK, FAK, IGF-1R, SRC, and VEGF-R2 human tumor-related protein kinases than the other compounds." (PMID 40137282, 2025). "IGF1R in tumor tissue had a median ΔCt value of -4.92 (IQR ±5.43), in non-tumor tissue -3.71 (IQR ±9.28), fold change 0.96 (IQR ±9.25) and p-value of 0.148." (PMID 40630212, 2025). "Expression of miR-335 can modulate the proliferation and invasion of tumor cells by affecting genes such as BRCA1, ER-α, and IGF1R." (PMID 41009512, 2025).
tumor (continued). "Co-targeting IGF-1R and STAT3 can inhibit tumor metastasis and overcome resistance to anti-IGF-1R therapy by preventing pro-angiogenic cytokine production and tumor angiogenesis." (PMID 39273251, 2024). "RNA levels of potential target genes IGF1R, NOTCH3 and OLFML2A were increased in 3D tumor spheroid culture compared to cells grown in 2-D culture to normal, ∼70% confluence." (PMID 38109320, 2024). "We noted that the expression of SERPINA3 and IGF1R/integrinα5β1 co-localized at areas of greater stromal interface, highlighting the potential interaction between the stroma and tumor cells via the SERPINA3 and IGF1R/integrinα5β1 axis." (PMID 38866016, 2024). "The silencing of IGF1R or treatment with antibodies binding IGF1 and IGF2, BI836845 or xentuzumab inhibited the growth of in vivo cocultured CAFs-tumor cell xenografts." (PMID 38892104, 2024). "Conversely, miR-615 has been reported to act as a tumor suppressor in HCC, while enhancing the anti-cytotoxic effect of NK cells, both achieved through the same target IGF-1R." (PMID 39906666, 2024). "Altogether, these results indicate that activation of IGF1R signaling promotes EMP and tumor progression toward a mesenchymal state in an ITGAV-mediated process, which facilitates the response to TME-derived factors, such as TGFβ." (PMID 39075581, 2024). "Since IGF-1R activation relies on ligand binding and elevated IGF-1 levels promote tumor growth in BC, reducing IGF-1 levels is considered a viable anti-cancer strategy." (PMID 39273251, 2024). "MiR-195 is also identified as a tumor suppressor in non-small cell lung cancer (NSCLC) cells, directly targeting the IGF-1R." (PMID 38331804, 2024). "Small molecules targeting IGF1R, including picropodophyllin (PPP) as well as the investigational drugs, BMS754807 and linsitinib, have been shown to increase the anti-tumor efficacy of chimeric antigen receptor (CAR) engineered T cells." (PMID 38420122, 2024). "In this regard, we have identified IGF1R activation as a key driver of EMP acquisition in mouse cSCC epithelial cancer cells, leading to tumor progression and an aggressive mesenchymal state in response to TGFβ." (PMID 39075581, 2024). "As an upstream regulatory factor, immature IGF-1R loses its ability to activate the PI3K/Akt/mTOR and MAPK/ERK pathways, thereby limiting tumor cell proliferation." (PMID 39199143, 2024). "Previous studies reported that IGFBP4 can inhibit the IGF1R pathway and AKT phosphorylation to suppress tumor growth, and p-AKT protein was identified as one of the proteins regulating EMT." (PMID 37349627, 2024). "SSTNIGF-1R (or SSTN92-119) mimics the docking site of αvβ3 and αvβ5 integrins and IGF-1R to prevent their interaction with CD138, thereby competitively disrupting the ternary complex and smothering pro-tumor pathways." (PMID 38655136, 2024). "We next evaluated the levels of p-ERK, p-AKTT308, p-AKTS473, p-EGFR, p-HER2, p-IGF1R, p-PDGFR, p-VEGFR and p-FGFR in tumor tissues." (PMID 38795180, 2024). "R1507 is a monoclonal antibody recognizing the insulin-like growth factor-1 receptor (IGF-1R), a receptor that plays an important role in tumor proliferation, apoptosis, angiogenesis, and metastasis." (PMID 39252946, 2024). "IGF2 acts to enhance IGF1R signaling within both the tumor and TME cells, supporting tumor regrowth and inducing feedback immunosuppression." (PMID 38853689, 2024). "The IGF-1R is activated in at least 50% of BCs, with its natural ligands, IGF-1 and IGF-2, contributing to tumor growth and survival." (PMID 39273251, 2024). "We further demonstrate that the activation of insulin-like growth factor-1 receptor (IGF1R) signaling pathway in epithelial cancer cells promotes ITGAV expression and induces EMP in response to tumor microenvironment (TME)-derived factors." (PMID 39075581, 2024). "One example is enhancing miR-122’s tumor-suppressing action by targeting ADAM10, IGF1R, cdk G1, and ADAM17." (PMID 38915826, 2024).
tumor (continued). "In tumor cells with an autocrine loop of IGF-2, targeting IGF1-R leads to compensatory upregulation of phosphorylated IR." (PMID 38331804, 2024). "Elevated amplification and mRNA expression of IGF-1R, along with increased protein levels of IGF-1R and phosphorylated-IGF-1R in tumor tissues and serum samples from NSCLC patients was observed." (PMID 39638246, 2024). "BCa cancer cells’ survival and spheroid-forming capability enhancement were induced by AKT phosphorylation due to IGF2/IGF1R induction, which was thought to be involved in molecular mechanism of SOX2 expression leading to poor tumor prognosis." (PMID 37196048, 2023). "Type 1 insulin-like growth factor receptor (IGF1R), an oncogene, is considered to be involved in the tumour progression by mediating the ATK signaling pathway; however, the specific mechanism of IGF1R in PCa is unclear." (PMID 37284313, 2023). "An example of utilizing miRNA targets is the attempt of enhancing the tumor-suppressing effect of miR-122, which targets ADAM10, IGF1R, as well as cyclin G1 and ADAM17." (PMID 37108330, 2023). "IGF-1R signaling through PI3K/AKT/mTOR complex 1 (mTORC1) has an important and well-documented role in enhancing cell growth, oncogenic transformation and tumor progression." (PMID 36835075, 2023). "IGF-1R is highly expressed in a variety of tumors, including HCC, and is involved in biological effects such as tumor-cell proliferation, differentiation, invasion, metastasis, and anti-apoptosis." (PMID 36698167, 2023). "In the same cases, the mean tumor staining intensity was 25 for VEGFR-2 (mean TBR 0.7), 7 for EGFR (mean TBR 0.9), 7 for IGF-1R (mean TBR 0.5), and 18 for CD40 (mean TBR 2)." (PMID 36979961, 2023). "For instance, activated IGF-1R signaling dampens FOXO3 signaling and thus reduces the expression of the proapoptotic protein Bim to inhibit tumor cell mitochondrial apoptosis by increasing the activity of the phosphorylated PI3K-Akt pathway." (PMID 36831629, 2023). "Activation of the oncogenic IGF-1R pathway by GPC3 leads to the initiation and maintenance of the tumor through inhibition of apoptosis and G1 cell cycle development." (PMID 37305177, 2023). "On the one hand, the downstream signaling pathway of IGF‐1R has multiple crossing sites with oncogenes such as Ras and c‐MYC, which can regulate each other to play a role in leading to tumor formation." (PMID 36994237, 2023). "Consistent with the effect of the IGF1R inhibitor linsitinib, shASS1/PYCR1 demonstrated a synergistic effect on tumour-proliferation inhibition with DDP in vitro and in vivo." (PMID 36978187, 2023). "IGF-1R can be phosphorylated by its ligand or autophosphorylated, subsequently being rapidly internalized to mediate IGF-1-induced signaling that promotes tumor cell growth and proliferation." (PMID 36831629, 2023). "In agreement with this, it has been found that the inhibition of LUNAR1 in CRC decreases tumour growth and efficiently depletes IGF1 pathway activity, indicating a role for the LUNAR1/NOTCH1/IGF1R axis in cancer development." (PMID 37628760, 2023). "By using RNA−Seq data of CRC patients from The Cancer Genome Atlas (TCGA) database, we divided the patients into normal group(58 patients)and tumor group(446 patients), and analyzed the expression and prognostic value analysis of IGF-1,IGF1R and RAGE." (PMID 36890832, 2023). "In conclusion, our analyses in an EWS tumor model show that EHD1 overexpression promotes oncogenesis by post-translationally upregulating the trafficking itinerary of an RTK, IGF-1R." (PMID 37474760, 2023). "In an MCF-7 mouse xenograft model, it was also observed that cotreatment with the IGF1R antibody, ganitumab, and PI3K signaling inhibitor, BYL719, was shown to induce tumor regression." (PMID 37237509, 2023). "It stimulates lymphangiogenesis through IGF1R/PI3K/AKT axis and aids in the spread of tumor lymph nodes." (PMID 37927475, 2023).
tumor (continued). "The PI3K/AKT inhibition by Idelalisib unexpectedly induces GSK3/FOXO1 activation, leading to the upregulation of IGF1R, which in turn activates the MAPK signaling in the Idelalisib-treated tumor cells." (PMID 36831678, 2023). "We previously demonstrated that IGF-1R activation increases the activity of stemness-related properties and sorafenib-refractoriness in HCC, thereby contributing to early tumor recurrence." (PMID 36765890, 2023). "As a result, it aids in carcinogenesis and cancer metastasis by increasing cell survival and proliferation while lowering tumor cell death via regulating several client proteins, including HER-2, IGF-1R, ER, EGFR, and cytokine receptors." (PMID 36902446, 2023). "Here, we found that BMI1, CD44, SOX2, OCT4, UBE2C, CXCR4 CSCs marker genes are significantly upregulated, while IGF1-R, KLF4, ALDH1A1, CD133, FAM3C are downregulated in the tumor core vs healthy mucosa of 24 patients with OSCC." (PMID 38096163, 2023). "EWAS results from bulk tumor tissue identified only one or two CpGs in HDAC4 and IGF1R as differentially hydroxymethylated in either cell type-adjusted or unadjusted model." (PMID 36909536, 2023). "IGF-1R mRNA and protein expression are increased in the serum from NSCLC patients, while IGF-1R downregulation in mice decreases tumor growth, proliferation, and vascularization." (PMID 36902237, 2023). "The low expression of miR-1294 can up-regulate the downstream target genes c-Myc, TPX2, IGF1R, and HOXA6 to promote the invasion and migration of ESCC, GM, OC, ccRCC tumor cells." (PMID 37303740, 2023). "The miR-375 gene is important for insulin secretion and glycogen synthase and acts as a tumor suppressor by downregulating numerous oncogenes, e.g. PDK1, JAK2, IGF1R, AEG-1, and suppressing the PI3K/Akt pathway." (PMID 35284957, 2022). "BMS-754807 is an inhibitor of targeting insulin-like growth factor-1 receptor/insulin receptor (IGF-1R/IR) signaling pathway, which has been proven to be effective in suppressing tumor cell proliferation of xenograft tumor models of several cancer types." (PMID 35069736, 2022). "The combination of IGF-1R and NPM–ALK inhibited tumor growth in a mouse model of ALCL cell lymphoma." (PMID 35211406, 2022). "In HCC, the liver tumors overexpress IGF1R, which is now directly fueled by the GH-induced hepatic IGF1 in the tumor milieu." (PMID 35865483, 2022). "The IGF-1/IGF-1R complex increases the expression of VEGF, which promotes angiogenesis and tumor development." (PMID 35203638, 2022). "By inhibiting or promoting IGF1R signaling, IGFBP5 can either act as a tumor suppressor or promoter." (PMID 36093095, 2022). "IGF-1R signaling and its downstream MAPK and PI3K/Akt play a major role in tumorigenesis and decrease the tumor latency time." (PMID 36568212, 2022). "AG1024 is a reversible, competitive inhibitor of insulin receptor (IR) and insulin-like growth factor 1 receptor (IGF-1R) that induces apoptosis, imparts anti-cancer activity, and significantly delays tumor growth." (PMID 35215353, 2022). "Meanwhile, the research found that miR-150-5p/3p can inhibit tumor migration and invasion both in vitro and in vivo by regulating insulin receptor substrate (IRS) 1 and the Insulin-like Growth Factor 1 Receptor (IGF1R)." (PMID 36235242, 2022). "Before exposing the tumor cells to IGF-1, expression of IGF-1R (DU145) and pIGF-1R (DU145, PC3) was verified by Facs analysis." (PMID 35053528, 2022). "IGF1R signaling is constitutively active in many human cancers and the IGF1R/AKT/MMP2 axis plays crucial roles in tumor invasion." (PMID 34976192, 2022). "MATN2 is localized downstream of several growth factor receptors, such as IGF-1R, GPER, and TGFβ1, and involved in tumor progression by stimulating the growth, chemotaxis, and migration of cancer cells." (PMID 35976950, 2022).
tumor (continued). "An interplay between IGFs, IGF1R, IGFBPs and IGFBP proteinases plus other modifying factors define a response of the cell, including its (un)responsiveness to potential tumor-suppressive agents." (PMID 36013453, 2022). "Among them, IGF1R and EGFR can activate PI3K/AKT and MEK/ERK signaling pathways, respectively, to enhance tumor progression and drug resistance, and YY1 activates Wnt/β-catenin signaling by promoting CTNNB1 expression to promote tumor growth." (PMID 36131281, 2022). "The IGF1R/IGF1 axis is a crucial progression factor for tumor cell development, supporting tumor cell survival, cell cycle, proliferation as well as cell growth, migration, invasion and angiogenesis." (PMID 35574343, 2022). "The creation of new types of combined IGF1R, autophagy, and/or TLR9 signaling inhibitors would play a significant role in the development of more personalized anti-tumor therapies." (PMID 35651701, 2022). "For instance, MK-0646, a type of monoclonal anti-IGF1R antibody, was found to induce apoptosis of colon cancer cells and inhibit growth of CRC cells in mice; the volume and weight of tumor xenografts were dramatically reduced in mice treated with MK-0646." (PMID 35296101, 2022). "To correlate the nuclear staining and localization of the tumor markers with outcome measures, we found it useful to partition patients into groups with low, medium, and high YAP/TAZ N:C ratio or IGF-1R/pIGF-1R mean nuclear intensity." (PMID 35284040, 2022). "Similar to EGFR, insulin-like growth factor type 1 receptor (IGF-1R) and platelet-derived growth factor receptor (PDGFR) also play a major role in tumor development and progression." (PMID 35241721, 2022). "In accordance with this, IGF1R and INSR act as oncogenes in PCa, enhancing tumor growth, proliferation, invasion, and angiogenesis." (PMID 35454907, 2022). "In clear cell RCC, SNHG12, as a competitive endogenous RNA, competes with miR-30a-5p to bind to downstream oncogenes RUNX2, IGF-1R and WNT2 to promote tumor cell invasiveness." (PMID 35597996, 2022). "First, WB and pathology results confirm IGF1R is ubiquitously found in MIA PaCa-2 cells and their tumor model, meanwhile MIA PaCa-2 cells are resistant to gemcitabine." (PMID 35794573, 2022). "Since KRAS mutations can lead to impaired mitochondrial respiration, this sophisticated reciprocal signaling node restores mitochondrial respiration in KRAS mutant tumor cells via SHH, IGF1R/AXL, and AKT." (PMID 36612058, 2022). "Synstatin, a mimetic peptide, inhibits the signaling complex formation between SDC-1, IGF1R, and integrin αvβ3 and attenuates HS-dependent angiogenic VEGF and FGF2 signaling, and blocks tumor angiogenesis in vivo." (PMID 36551220, 2022). "Of note, Insr expression was found upregulated in mouse lungs with compromised IGF1R signaling, and IGF1 expression by the TME was reported to have a supportive role in tumor initiation and progression." (PMID 35688943, 2022). "To verify the potential impact of glycemic metabolism and genomic alterations, we performed immunohistochemistry analysis for AR, IR-α, IR-β, IGF1-R and PSMA expression in the primary tumor." (PMID 36077746, 2022). "Therefore, IGF2R may act as a tumor suppressor by preventing IGF1R activation." (PMID 35597813, 2022). "The modulation of both VEGF expression and tumor angiogenesis is also driven by molecules belonging to HIF1α and insulin-like growth factor 1 (IGF1)/insulin-like growth factor 1 receptor (IGF1R) signaling." (PMID 36432658, 2022). "Regarding the SUMO ligase RanBP2, it has been observed its implication in the stability of insulin-like growth factor-1 receptor (IGF-1R), involved in tumor growth and survival." (PMID 35887358, 2022).